FOXP3 (forkhead box P3)
Diseases named in the same sentence as FOXP3 in open-access papers (continued):
Sharing a sentence is not in itself a finding about the gene and the disease.
IPEX syndrome (145 papers, 2008 to 2026). "In this report, we describe the clinical and immunologic consequences of a novel FOXP3 variant in an infant with refractory IPEX syndrome." (PMID 41909206, 2026). "Genetic testing identified a hemizygous pathogenic variant in FOXP3 (c·1040 G > A, p.Arg347His), establishing a diagnosis of IPEX syndrome." (PMID 42092823, 2026). "In IPEX syndrome, FOXP3 deficiency indirectly impairs B cell tolerance by disrupting Treg-mediated regulation of peripheral tolerance checkpoints." (PMID 40804844, 2025). "Hemizygous mutations in FOXP3, which is located on the X chromosome, manifest in human male subjects as IPEX syndrome." (PMID 41142805, 2025). "IPEX syndrome typically affects male infants and is linked to forkhead box P3 (FOXP3) variants; phenotype, sex, age at onset, and genetics did not fit our case." (PMID 41169469, 2025). "IPEX syndrome (immunodysregulation-polyendocrinopathy-enteropathy x-linked) is caused by hemizygous mutations in the FOXP3 gene, which encodes the basic transcription factor of regulatory T cells." (PMID 39962262, 2025). "The link between FOXP3 mutations and IPEX syndrome, inflammatory bowel disease, and severe allergy further underscored its essential role in immune tolerance." (PMID 41226379, 2025). "The lymphoproliferation and multiorgan inflammation seen in cDKO mice are widespread but are delayed relative to that observed in FOXP3 mutation or deficiency associated with scurfy mice and IPEX syndromes." (PMID 40794436, 2025). "IPEX syndrome is caused by pathogenic variants in the Forkhead Box P3 (FOXP3) gene, encoding for the lineage-specific transcription factor that controls T regulatory (Treg) cell signature." (PMID 40977713, 2025). "IPEX syndrome is characterized by mutations in the FOXP3 gene, which cause altered regulatory T cell function, lastly leading to immune overactivity in response to antigen stimulation." (PMID 41025025, 2025). "Singh and colleagues describe a CRISPR-Cas9-based gene editing strategy to treat IPEX syndrome, a monogenic immune disorder caused by mutations in the FOXP3 gene." (PMID 38282895, 2024). "IPEX syndrome, caused by FOXP3 mutations, is a devastating disease that leads to substantial mortality." (PMID 38282895, 2024). "IPEX syndrome occurs due to mutations in the forkhead box P3 (FoxP3) gene, resulting in impaired Treg maturation." (PMID 37795085, 2023). "IPEX syndrome was diagnosed because of the presence of a hemizygous mutation in FOXP3 gene (c.543C>T (p.S181S) in the exon 5)." (PMID 36713411, 2023). "Pathogenic variants in FOXP3 cause IPEX syndrome (immune dysregulation, polyendocrinopathy, enteropathy, X-linked), an IEI characterized by autoimmunity, lymphoproliferation and severe atopy." (PMID 37727514, 2023). "In the IPEX syndrome (Immune dysregulation, Polyendocrinopathy, Enteropathy, X-linked) caused by loss-of-function mutations in FOXP3 leading to loss of regulatory T cells is an apt example." (PMID 37235056, 2023). "Mutations in the FOXP3 gene, on the X chromosome, cause IPEX syndrome with abrogated Treg development." (PMID 38022498, 2023). "The ClinVar database lists five splice site mutations in the FOXP3 gene observed in patients with IPEX syndrome." (PMID 37895245, 2023). "Of all the 44 distinct FOXP3 mutations associated with IPEX syndrome, 11 were splicing-associated mutations." (PMID 37895245, 2023). "We report a large cohort of patients with IPEX syndrome (n = 65) resulting from a hemizygous FOXP3 pathogenic variant identified by custom gene panel testing for monogenic NDM." (PMID 36600150, 2023). "IPEX syndrome is caused by mutations of the FOXP3 gene located in the short arm zone (Xp11.23) of the X chromosome." (PMID 36980146, 2023). "More than 70 mutations in the Foxp3 gene have been identified in IPEX syndrome, ranging from a single base substitution through deletion mutations." (PMID 35359918, 2022).
IPEX syndrome (continued). "At the age of 14 years, the patient was diagnosed with IPEX syndrome due to a c.748-750del (p.Lys250del) mutation in the leucine zipper domain of the FOXP3 protein." (PMID 36479284, 2022). "The incidence of IPEX syndrome is less than one in a million, and to date, more than seventy pathogenic mutations of FOXP3 have been described in over 200 patients." (PMID 36091011, 2022). "Deficiency in Treg number or function leads to a group of disorders known as ‘Tregopathies’, the prototype condition being IPEX syndrome (immune dysregulation, polyendocrinopathy, enteropathy, X-linked) caused by mutations in FOXP3 gene." (PMID 35241125, 2022). "Mutations in FOXP3 lead to IPEX syndrome, which should be considered in males with the following clinical signs: early-onset IBD, endocrinopathy (most commonly type 1 diabetes mellitus and autoimmune thyroid disease), and dermatitis (most commonly eczema)." (PMID 36177048, 2022). "Here we report the case of a late diagnosis of IPEX syndrome in a Brazilian patient harboring an already reported mutation in FOXP3 gene with a mild phenotype." (PMID 36503523, 2022). "Genetic conditions are related to the mutation within the transcription factor Foxp3 which was found in nearly 60% of patients with IPEX syndrome." (PMID 35207219, 2022). "For example, PAS mutations in the FOXP3 gene lead to downregulation of FOXP3, a key transcription factor for regulatory T cells, resulting in IPEX syndrome, a fatal autoimmune disorder linked to defective development of regulatory T cells." (PMID 35222412, 2022). "Here we report the case of a Brazilian patient with juvenile idiopathic arthritis, eczema and vitiligo as the clue for the late diagnosis of IPEX syndrome harboring the A384T mutation in the FOXP3 gene." (PMID 36503523, 2022). "Immune dysregulation polyendocrinopathy, enteropathy, X-linked (IPEX), also known as X-linked autoimmunity-immunodeficiency syndrome, is caused by mutations in FOXP3 gene." (PMID 34584998, 2021). "In the literature, over 70 FOXP3 mutations associated with IPEX syndrome have been reported, but the relationship between the genotype and phenotype of IPEX syndrome needs explanation." (PMID 33668198, 2021). "IPEX syndrome is caused by loss of function of X linked gene, FOXP3 and characterized by immunodysregulation, polyendocrinopathy, enteropathy." (PMID 34887872, 2021). "IPEX syndrome is a rare monogenic primary immunodeficiency caused by FOXP3 LOF mutations, which encodes a pivotal transcription factor required for the development of regulatory T cells." (PMID 34858394, 2021). "For example, patients suffered from IPEX syndrome have FOXP3 mutations that leads to a reduction of the number of Foxp3+ Treg cells; many RA patients have relatively normal number of Treg cells, but a lot of them show impaired suppression of self-antigens." (PMID 33912156, 2021). "As such, maintenance of the expression of both isoforms must be further investigated in future gene editing strategies aimed at fully restoring FOXP3 functions in FOXP3-deficient cells such as those in IPEX syndrome patients." (PMID 34737751, 2021). "The clinical features and gene mutations of FOXP3 of previously reported IPEX syndrome patients presenting with severe gastritis." (PMID 33546062, 2021). "Dysfunction and mutations of the FoxP3 gene causes immunodysregulation polyendocrinopathy enteropathy X-linked (or IPEX) syndrome." (PMID 34093553, 2021). "The first disorder associated with dysfunction of the Foxp3 gene impacting Tregs, is IPEX syndrome (immunodysregulation polyendocrinopathy enteropathy X-linked)." (PMID 34294806, 2021). "The signs and symptoms of IPEX syndrome are related to the genetic changes in FOXP3: nonsense variants, missense variants, small in-frame amino acid deletions or insertions, and splice site variants." (PMID 33668198, 2021). "Natural mutations in the FOXP3 gene cause the fatal autoimmune Scurfy phenotype in mice and IPEX syndrome in humans." (PMID 34299063, 2021).
IPEX syndrome (continued). "IPEX syndrome is a rare disorder of the immune regulatory system caused by mutations of forkhead box P3 (FoxP3), which is a transcription factor responsible for the generation and maturation of Tregs (CD4+ CD25+ FoxP3+)." (PMID 34792685, 2021). "Next-generation sequencing revealed 2 novel variants in gene FOXP3 in the patients who were diagnosed with the IPEX syndrome." (PMID 33546062, 2021). "With awareness of IPEX syndrome and recognition of FOXP3 gene mutations, an increasing number of atypical IPEX syndrome patients have been identified." (PMID 33546062, 2021). "IPEX syndrome has heterogeneous clinical presentation and evolution; hence, finding FOXP3 mutation is at the same time challenging and paramount for the child prognosis." (PMID 33692972, 2021). "In IPEX syndrome FOXP3 deficiency causes metabolic reprogramming of Tregs with heightened aerobic glycolysis, mainly due to mTORC2 deregulation." (PMID 33692972, 2021). "This is illustrated by the systemic autoimmune syndrome observed in Scurfy mice and Immunodysregulation Polyendocrinopathy Enteropathy X-linked (IPEX) patients who carry mutations in Foxp3 and after the ablation of Treg cells in young and adult mice." (PMID 33143070, 2020). "Since the monogenic primary immunodeficiency IPEX syndrome was defined more than 170 distinct FOXP3 mutations have been reported." (PMID 33194927, 2020). "Analysis of FOXP3 mutations from patients and patients' mothers promptly confirm IPEX syndrome diagnosis and identify IPEX mutation carrier, respectively." (PMID 33194927, 2020). "IPEX (immune dysregulation, polyendocrinopathy, enteropathy, X-linked) syndrome is an autoimmune disease caused by mutations in FoxP3 that lead to Treg dysfunction." (PMID 31572365, 2019). "Foxp3 deficiency causes severe autoimmune diseases in both human and mice as shown in IPEX syndrome (immune dysregulation, polyendocrinopathy, enteropathy, X-linked) patients and scurfy mice, respectively." (PMID 31434282, 2019). "Immunodysregulation polyendocrinopathy enteropathy X-linked (IPEX) is caused by mutations in FOXP3, a master regulator of T regulatory cells (Treg), and consequently results in defective T cell-mediated peripheral tolerance." (PMID 29651287, 2018). "There is evidence that autoantibodies to harmonin and villin are diagnostic markers for individuals with IPEX syndrome, although we were unable to test this in our individuals with hemizygous FOXP3 mutations." (PMID 29417186, 2018). "IPEX syndrome is a hereditary immunodeficiency characterized by the loss of function of FOXP3-expressing Tregs." (PMID 29503652, 2018). "At around same time, mutations in FOXP3 gene and its 3′ untranslated region were confirmed in human patients of IPEX syndrome." (PMID 29887862, 2018). "Multicenter retrospective study of patients diagnosed with IPEX syndrome caused by mutations in FOXP3." (PMID 30385752, 2018). "The central role of the FoxP3 transcription factor in maintaining immune homeostasis is best exemplified by the systemic autoimmune disease IPEX syndrome which affects individuals carrying mutations in FOXP35." (PMID 29487369, 2018). "Here we present the case of a pediatric patient with metaplastic atrophic gastritis in whom IPEX syndrome was confirmed by FOXP3 gene mutation." (PMID 29907148, 2018). "In humans, Foxp3 mutations result in immunodysregulation, polyendocrinopathy, and enteropathy, with X-linked inheritance (called IPEX syndrome)." (PMID 29270168, 2017). "For example, Foxp3 deficiency results in IPEX syndrome that is characterized by expression of multiple autoimmune disorders." (PMID 29138503, 2017). "An example is a polyadenylation signal mutation (AAUAAA → AAUGAA) in the FOXP3 (forkhead box P3) gene causing the IPEX syndrome, which is characterized by immune dysfunction, polyendocrinopathy and enteropathy." (PMID 24408965, 2014).
IPEX syndrome (continued). "FOXP3 is also found in human Tregs and mutations in FOXP3 cause the IPEX syndrome (Immune dysregulation, Polyendocrinopathy, Enteropathy, X-linked)." (PMID 24605111, 2014). "A thymic biopsy showed absent CD1a and increased Bcl-2 (an anti-apoptotic protein) expression, due to a four point mutation in FOXP3 leading to translational frameshift, which is similar to IPEX syndrome." (PMID 22816667, 2012). "IPEX syndrome is a congenital disorder of immune regulation caused by mutations in the FOXP3 gene, which is required for the suppressive function of naturally arising CD4 + CD25 + regulatory T cells." (PMID 22816667, 2012). "Genetic testing identified a mutation in the FOXP3 gene, confirming the diagnosis of IPEX syndrome." (PMID 41060163, 2025). "Mutations in FOXP3 result in IPEX syndrome in humans and a similar scurfy phenotype in mice." (PMID 40794436, 2025). "Since then, IPEX syndrome is also named according to the molecular defect as FoxP3 deficiency." (PMID 38507159, 2024). "In mice, Foxp3 gene mutation results in the scurfy (SF) mouse model, which serves as a unique model for a rapidly fatal disease characterized by immune dysregulation, polyendocrinopathy, enteropathy, and X-linked inheritance (human IPEX syndrome." (PMID 38398835, 2024). "It is known that FOXP3 mutations impair Treg cell development and cause IPEX syndrome." (PMID 38674427, 2024). "Mutations in the transcription factor forkhead box P3 (FOXP3) gene lead to IPEX syndrome." (PMID 36788146, 2023). "A recent study on 15 individuals with IPEX syndrome showed that demethylation at the TSDR increased gradually with disease progression, having normal values in new-born blood spot samples from individuals with pathogenic FOXP3 variants that increased as IPEX syndrome developed in early life." (PMID 36600150, 2023). "However, in a cohort of 173 patients with IPEX syndrome symptoms, only 50.9% had direct mutations in FOXP3, underscoring the fragility of Treg function and its sensitivity to modulation of alternative pathways." (PMID 36032083, 2022). "Hemizygous mutations in FOXP3 located on the X chromosome result in IPEX syndrome (immune dysregulation, polyendocrinopathy, enteropathy, X-linked) classically presenting in the first few weeks of life with severe enteropathy, eczema and type 1 diabetes mellitus." (PMID 35241125, 2022). "Early descriptions of FoxP3 deficiency in humans resulted in “X-linked autoimmunity-allergic dysregulation syndrome” and “Immunodysregulation polyendocrinopathy enteropathy X-linked” (IPEX) syndrome." (PMID 35572516, 2022). "Importantly, four patients had dual diagnoses with glucose-6-phosphate dehydrogenase (G6PD) deficiency: X-linked SCID (IL2RG), C6 deficiency (C6), IPEX syndrome (FOXP3), DiGeorge syndrome (TBX1)." (PMID 35757720, 2022). "Here, we present a rare case of IPEX syndrome caused by a novel variant of FOXP3." (PMID 35186001, 2022). "We present a rare cause of male fetal hydrops in the context of IPEX syndrome and discuss FOXP3 gene variants as a differential for ‘unexplained’ fetal hydrops that may present after the first trimester." (PMID 33637067, 2021). "IPEX syndrome is a result of the X-linked recessive disorder of FOXP3 and usually affects boys." (PMID 33668198, 2021). "Similarly, humans born with dysfunctional FoxP3 develop an autoimmune syndrome called immunodysregulation polyendocrinopathy enteropathy X-linked (IPEX), which is characterized by severe enteropathy, endocrinopathy, and eczematous dermatitis." (PMID 34193955, 2021). "Subsequently, mutations in the FOXP3 gene, which codes for a DNA-binding factor with homology to Forkhead family proteins, were found to be associated with the IPEX syndrome, following the discovery of a frameshift mutation in Foxp3 observed in a naturally occurring mutant mouse." (PMID 30443250, 2018).
IPEX syndrome (continued). "Foxp3 has been shown to be the key regulator of Treg cell differentiation and function, as demonstrated by the devastating effects of loss-of-function mutations in the Foxp3 gene, leading to the lethal IPEX syndrome (immune dysregulation, polyendocrinopathy, enteropathy, X-linked)." (PMID 24069022, 2013). "This study demonstrated that HAA and VAA measured by LIPS are accurate diagnostic markers of the IPEX syndrome, with 100% concordance with FOXP3 gene mutations, that differentiate IPEX, including atypical cases, from other childhood disorders associated with enteropathies." (PMID 24250806, 2013). "In mice, spontaneous or gene-targeted Foxp3 deficiency leads to death by 3-4 weeks of age due to the development of a fatal multiorgan autoimmune syndrome that recapitulates many clinical features of the human IPEX syndrome." (PMID 23691523, 2013). "The finding that the regulatory T cell population in APECED is functionally defective and that the expression of the key molecule for Treg function, the FOXP3 is impaired, is consistent with clinical findings in IPEX syndrome, caused by a defect in the function of the FOXP3 gene." (PMID 22876245, 2012). "However, the same pathogenic variant has been detected in patients with different clinical manifestations, suggesting the role of genetic modifiers, such as variants in genes encoding for protein partners of FOXP3, and epigenetic factors in determining the expressivity of IPEX syndrome." (PMID 40977713, 2025). "In FOXP3, loss of dimerization capacity as a result of an in-frame single amino acid deletion in the leucine zipper domain results in an immunological disorder known as IPEX syndrome (MIM 304790), with disease severity comparable to that resulting from loss of DNA-binding activity in FOXP3." (PMID 27933109, 2016). "Foxp3 mutant scurfy (SF) mice, a model of human IPEX syndrome, exhibit an autoimmune phenotype even under germ-free conditions, due to the loss of regulatory T cell (Treg)-mediated control of inflammatory effector T cells." (PMID 40649913, 2025). "The amount of DNA demethylation at FOXP3 promoter/enhancer regions is always higher in patients with IPEX syndrome." (PMID 41142805, 2025). "APS-1 and IPEX syndrome are monogenic disorders, caused by mutations in the autoimmune regulator (AIRE) and forkhead box protein P3 (FOXP3) genes, respectively." (PMID 36980146, 2023). "Different patterns of peripheral FOXP3 expression have been reported in IPEX syndrome and differently from what is expected, normal to high expression can also be observed." (PMID 36503523, 2022). "Defects in the transcription factor FOXP3 which is required for the normal development and function of T regulatory cells (Tregs) results in IPEX syndrome and the clinical manifestations of enteropathy, type I diabetes mellitus and eczema." (PMID 35783679, 2022). "An additional limitation of viral gene-addition approaches in IPEX syndrome is that they cannot be applied to HSCs due to the toxicity of FOXP3 on HSCs in terms of stem cell proliferation and differentiation." (PMID 35783679, 2022). "We analyze T regulatory cells by surface staining with CD4+CD25+CD127+ or by analysis of intracellular FOXP3 expression in suspected cases of IPEX syndrome." (PMID 31572360, 2019). "Ectopic expression of the FOXP3 gene in naive human CD4+ T cells from healthy donors or IPEX syndrome patients renders the cells suppressive." (PMID 29535721, 2018). "Mutations of this domain were observed in the Scurfy mouse and in the corresponding human IPEX syndrome, leading to a cytoplasmic accumulation of FOXP3." (PMID 28903735, 2017). "In light of these findings and in order to challenge different approaches for a hematopoietic stem cell (HSC)-based gene therapy for IPEX syndrome, we addressed here the effect of FOXP3 constitutive expression in the differentiation and homeostasis of HSC." (PMID 29150659, 2017).